IL10 (interleukin 10)
Diseases named in the same sentence as IL10 in open-access papers (continued):
Sharing a sentence is not in itself a finding about the gene and the disease.
asthma (continued). "In line with this, several studies reported diminished antigen-induced, peripheral blood mononuclear cell (PBMC)-derived IL-10 production in children and adults with atopic disorders (AR, asthma, or atopic dermatitis)." (PMID 29616018, 2018). "IL-10-differentiated dendritic cells (DC10) can reverse the asthma phenotype in mice, but how they suppress the asthmatic B cell response is unclear." (PMID 29293622, 2018). "The adoptive transfer of these CD9+ B cells alone is thus sufficient to abrogate asthma in an IL-10-dependent manner." (PMID 30622536, 2018). "Allergic rhinitis and complication groups had significantly different IL-5 and IL-10 levels (P<0.05, P<0.01), and the asthma group had significantly different ILs levels from those of the complication group (P<0.01, P<0.01, P<0.05)." (PMID 30344593, 2018). "When peripheral blood mononuclear cells (PBMC) from children with severe therapy-resistant asthma were stimulated with dexamethasone, release of IL-10 was significantly lower than that from control PBMC." (PMID 29948729, 2018). "IL-10 was reported to inhibit eosinophil-induced inflammatory effects of asthma, suggesting that IL-10 plays a key negative regulatory role in the development of allergic asthma." (PMID 30294594, 2018). "IL-10 is an anti-inflammatory cytokine notably produced by T cells and B cells during the asthma reaction." (PMID 30147700, 2018). "We have previously demonstrated that murine IL-10+ Bregs are enriched in a CD9+ B cell subset and that adoptive transfer of CD9+ B cells alone is sufficient to abrogate asthma in an IL-10-dependent manner." (PMID 30622536, 2018). "In the present study, the potential role of two key cytokines of IL-10 and IL-17A was investigated in asthma pathogenesis." (PMID 30915130, 2018). "The production of IL-10 from these retrogenic B cells and the induction of IL-10 expressing Tr1 cells achieved allergen-specific immune tolerance against asthma." (PMID 29503652, 2018). "Flow cytometry analysis of IL-10GFP transgenic mice showed that asthma sensitization increases the frequency of IL-10-producing cells in the lungs." (PMID 30147700, 2018). "Asthma-induced Brucella susceptibility appears to be dependent on CD4+ T cells, the IL-4/STAT6 signaling pathway and IL-10, and is maintained in IL-12- and IFN-γR-deficient mice." (PMID 30147700, 2018). "IL-10 impairs the immunosuppressive activity of Tregs in murine models of schistosomiasis japonica or asthma." (PMID 30116243, 2018). "The normalized expression of IL10 showed a statistically significant different pattern of expression in mild and severe asthma with each other (P=0.0001) and with healthy control (P= 0.293 and 0.001, respectively." (PMID 30915130, 2018). "In a study using S. japonicum-infected or OVA sensitized asthma murine models, both in vivo and in vitro data proved that IL-10 has opposite regulation on Treg cells." (PMID 30233389, 2018). "Further, the levels of IL-17, TGF-β, and IL-10 during asthma onset are good surrogates for the numbers of Th17 and Treg cells." (PMID 28674387, 2017). "It was observed that the PDT treatment (A+P+TP+PDT) in asthmatic mice increases the IL-10 production in the BAL when compared to the Asthma + P group (A+P)." (PMID 29145431, 2017). "IL-10, in turn, has a regulatory and an anti-inflammatory function, and it inhibits antigen presentation in macrophages/monocytes in asthma disease." (PMID 28670318, 2017). "Effective treatment with AEBSF or nafamostat mesilate on experimental asthma induced the production of IL-10." (PMID 29073215, 2017). "Defective IL-10 expression has been associated with increased steroid resistance in children with severe asthma, and vitamin D enhances the frequency of both IL-10+ and Foxp3+ Treg cells in children with severe asthma." (PMID 28725641, 2017). "Conversely, induction of the T cell-driven IL-10 response is well-known to mitigate diseases in mice ranging from asthma and inflammatory bowel disease to multiple sclerosis." (PMID 28742882, 2017).
asthma (continued). "Concurrently, levels of IFN-γ, IL-4, and IL-17A in serum, lung tissues, and BALF increased in RSV-infected asthma mice while levels of IL-10 declined." (PMID 29123203, 2017). "Serum IFN-γ, IL-4, and IL-17A levels were increased in RSV and asthma mice compared with control mice while IL-10 levels were decreased." (PMID 29123203, 2017). "This gene set includes numerous cytokines that mediate Th2 cell signaling associated with asthma (IL3, IL4, IL5, IL9, IL10 and IL13), as well as components of the IgE receptor (FCERA, FCERG, MS4A2) and eosinophil granule proteins (ECP, EDN, EPX, and MBP)." (PMID 28854632, 2017). "Such as asthma patients showed lower serum levels of IL-10, which positively correlated with the lung function." (PMID 28086216, 2017). "The Smteg treated mice presented significant increased percentage of CD11b+F4/80+IL-10+ and CD11c+CD11b+IL-10+ cells compared to Asthma group." (PMID 27454771, 2016). "The percentage of γδTCR+CD3+, IL-9+CD3+, IL-9+γδT lymphocytes was higher, whereas the percentage of IL-10+ CD3+ lymphocytes was lower in the asthma control group than in the normal control group (P < 0.001)." (PMID 27518187, 2016). "The present study demonstrates that empirical prescriptions of TCM can effectively control asthma attacks and reduce the levels of IL-10, IL-17, and MMP-9 in peripheral blood." (PMID 27378824, 2016). "The importance of these findings is based on the fact that patients with asthma produce less IL-10, suggesting the fundamental role of the cytokine as mediator of immunological tolerance in the airways." (PMID 28066430, 2016). "Ciglitazone treatment also reduces the production of ovalbumin (OVA)-specific IgE, and rosiglitazone treatment increases the production of IL-10 and suppresses the migration of dendritic cells (DCs) to lymph nodes, ameliorating the severity of asthma." (PMID 27548145, 2016). "A previous study demonstrated that endogenous IL-10 is critical for the development of asthma-like responses in a murine asthma model wherein asthma was induced following i.p. sensitization and subsequent intranasal challenge with ovalbumin (OVA)." (PMID 27584662, 2016). "In humans, IL-10 potentiates IgG4 production and decreases IgE synthesis, an action important for asthma modulation." (PMID 27454771, 2016). "The plasma levels of IL-10 and IL-12 were decreased by 29.8% and 100% in the patients with AR, by 54.3% and 100% in the patients with asthma, and by 100% and 100% in the patients with AR + AS, respectively." (PMID 27057098, 2016). "group had lower airway hyperresponsiveness, percentages of γδTCR+CD3+ and IL-9+CD3+ lymphocytes, and IL9+γδT cells, and higher percentages of IL-10+CD3+ lymphocytes and IL-10+γδT cells compared to the asthma control group." (PMID 27518187, 2016). "In asthma, there are a number of studies both in patients and in animal models that demonstrate a potential role of IL-10 regulating inflammation in the airways, where the main source is CD4+ CD25+ T-lymphocytes." (PMID 27795621, 2016). "Accordingly, cytokines associated with suppressed function in asthma (IFN-γ and IL-10) which could be secreted by Treg cells increased in the treated compared with the untreated group, whereas cytokines associated with attack and progression of asthma (IL-4 and IL-5) decreased." (PMID 27527926, 2016). "To elucidate the immunologic mechanism of TCM in the treatment of asthma, we examined the expression of some more cytokines related to asthma, including IL-10, IL-17, TGF-β1, and MMP-9 in this study." (PMID 27378824, 2016). "Understanding the mechanisms by which innate IFNs and IL-10 interact will provide important information for the identification of their role in virus-induced asthma." (PMID 25430775, 2015). "DCs genetically engineered to express IL-10 have been reported to induce long-lasting antigen-specific tolerance in experimental asthma models." (PMID 25860995, 2015).
asthma (continued). "This review attempts to shed light on MØ IL-10 and innate IFN interactions and discusses the role of IL-10 in virus-induced asthma exacerbations." (PMID 25430775, 2015). "In mouse asthma exacerbation models, IL-10 augments eosinophilic inflammation, airway hyperresponsiveness (AHR), mucus metaplasia, IL-5 production, and airway remodeling, and M2 phenotype MØs were suggested to contribute to the pathogenesis of disease." (PMID 25430775, 2015). "Children in Class 5 (all of whom produced high levels of IL‐13, and almost all produced high levels of IL‐5, with some production of IL‐10 and IFN‐γ) had a fivefold increase in the risk of asthma." (PMID 26061524, 2015). "IL-10 and IL-4 production was shown to be induced by peripheral blood leukocytes from patients with asthma after exposure to the mite allergen D. farinae." (PMID 25918735, 2015). "The production in the lung of antiviral innate IFNs and immunosuppressor cytokine IL-10 plays an important role in virus-induced asthma exacerbations, but their interactions are poorly understood." (PMID 25430775, 2015). "It has also been suggested that exercise training modulates allergic inflammation by increasing the expression of the anti-inflammatory cytokines IL-10 and IL-1ra in an animal model of asthma." (PMID 26487563, 2015). "Functional defects in IL-10-producing CD4+ Tr1 cells have also been described in asthma and rheumatoid arthritis." (PMID 25852682, 2015). "This is something that needs to be explored further, especially when IL-10 is suggested as a potential therapy in allergy and asthma." (PMID 25430775, 2015). "This review attempts to shed light on macrophage IL-10–IFNs interactions and discusses the role of IL-10 in virus-induced asthma exacerbations." (PMID 25430775, 2015). "Oral calcitriol, compared with placebo, therapy of the patients with SR asthma significantly improved dexamethasone-induced IL-10 production in vitro while suppressing dexamethasone-induced IL-17A production." (PMID 25772594, 2015). "Conversely, calcitriol therapy also restores the impaired, corticosteroid-induced anti-inflammatory IL-10 response that characterizes patients with SR asthma, extending our earlier findings in this area." (PMID 25772594, 2015). "We determined the levels of 6 cytokines implicated in asthma, which can be divided by the response profiles Th1 (TNF-α and IL-6) and Th2 (IL-4, IL-13, IL-10, and IL-5)." (PMID 26101464, 2015). "Children in Class1 (‘IL‐10 expressors’) had a relatively low risk of HDM sensitization, asthma, and wheeze." (PMID 26061524, 2015). "In some murine models of asthma, IL-10 can suppress allergic inflammation in the lung, but amounts of this cytokine were similar in lungs of mice sensitized using high or low doses of LPS (data not shown)." (PMID 24168764, 2014). "Vitamin D is able to modulate the function of CD4+ T cells particularly reversing the defective induction of IL-10-secreting regulatory T cells in glucocorticoid-resistant asthma patients." (PMID 25061262, 2014). "IL-10 has been suggested as a treatment of asthma because of its immunosuppressive and anti-inflammatory properties." (PMID 25409540, 2014). "Overall, our results suggest a role of TGF-β1 in olive pollen sensitization and TNF-α and IL-10 genotypes in the asthma induced by specific olive pollen allergens." (PMID 25759826, 2014). "In Costa Rica, a study of 417 children and 503 participants of a childhood asthma management program highlighted the role of IL10 in allergy and asthma exacerbations (when exposed to dust mites)." (PMID 25238536, 2014). "Many previous reports have demonstrated that the regulation of asthma reactions by parasitic infection is related closely to the up-regulation of IL-10." (PMID 25409540, 2014). "In conclusion, these results suggest a role of TGF-β1 in olive-pollen sensitization and TNF-α and IL-10 genotypes in the asthma induced by specific olive-pollen allergens." (PMID 25759826, 2014).
asthma (continued). "We found that the accumulation of MDSCs, which was positively correlated IL-10 levels and negatively correlated with IL-12 levels, is significantly increased during the onset of asthma in both human and mice." (PMID 23717481, 2013). "During the onset of asthma, the accumulation of MDSCs and the level of serum IL-10 increase, while the level of IL-12 decreases." (PMID 23717481, 2013). "Finally, IL-10 polymorphisms may be associated with asthma severity as well as susceptibility." (PMID 23335974, 2013). "This prompted us to ask how MDSCs, IL-10, and IL-12 levels are regulated in asthmatic mice and what the possible mechanism of asthma onset is." (PMID 23717481, 2013). "The amount of MDSCs in peripheral blood was positively correlated the level of IL-10 in the serum of the patients with asthma attacks (r = 0.741, P<0.01) and negatively correlated with the level of serum IL-12 (r = −0.879, P<0.01)." (PMID 23717481, 2013). "In a rodent model of experimental asthma, electroacupuncture increased IL-1 and IFNγ and decreased IL-4, IL-10, nitric oxide, and leukotriene B4 in bronchoalveolar lavage and pulmonary tissue compared with control and sham acupuncture groups." (PMID 23476696, 2013). "This further illustrates the importance of steroid-induced IL-10 in the treatment of asthma and atopy." (PMID 23755052, 2013). "In mild asthma, Il10 showed the largest change in expression followed by II5, II4, Tnfα, Il6, Il2, Il13, and Ifnγ, respectively." (PMID 23781124, 2013). "In severe asthma, the largest change (110-fold) is observed in Ifnγ expression followed by Il13, Il2, Il4, Il10, Il6, Il5, and Tnfα, respectively." (PMID 23781124, 2013). "Taken together, these studies strongly suggest that MDSCs contribute to the onset and development of asthma by up-regulating the level of IL-10 and down-regulating the level of IL-12." (PMID 23717481, 2013). "To better understand the function of the key cytokines and immune cells during the asthma onset and development in detail, we examined the levels of MDSCs, IL-10, and IL-12 in children and mice." (PMID 23717481, 2013). "The asthma group mice exhibited significantly higher levels of MDSCs and IL-10 than in the normal control mice, and budesonide treatment greatly reduced their expressions." (PMID 23717481, 2013). "Stimulation of macrophages by ovalbumin uptake and TLR ligands induced increased production of IL-10 by these macrophages, and this resulted in lower levels of IL-5 and ovalbumin-specific IgE and a lower number of eosinophils in a mouse model of asthma." (PMID 23533311, 2013). "GMCSF, IFN-γ, IL-5, IL-8 and IL-10, on the other hand, were significantly decreased in children with asthma (p 0.003, 0.03, 0.001, 0.004 and 0.03, respectively)." (PMID 23286340, 2013). "To validate our conclusion from the patient study and to investigate the mechanism of asthma onset and the possible role of MDSCs, IL-10, and IL-12 during onset, we used mouse models." (PMID 23717481, 2013). "The study on asthma induced by virus infection demonstrated high level of IL-10 during disease onset, which is consistent with our observations." (PMID 23717481, 2013). "The percentage of MDSCs in children with asthma was positively correlated with the level of serum IL-10 and negatively correlated with the level of serum IL-12." (PMID 23717481, 2013). "IL-10 has broad immunosuppressive and anti-inflammatory actions relevant to the inhibition of asthma pathology." (PMID 23738146, 2013). "Since Haemophilus influenzae is the pathogen most strongly associated with asthma and COPD, we analyzed the ability of three different Prevotella strains to modulate Haemophilus-induced IL-23, IL-12p70 and IL-10 production in DCs." (PMID 22363778, 2012). "It has been shown that asthma patients have lower numbers of Treg cells with an impaired activity and the importance of IL-10 stimulation in the amelioration of asthmatic symptoms is already well established." (PMID 23091602, 2012).
asthma (continued). "Human NKT cells can produce cytokines IL-4 and IL-10, which promote Th2 cell generation and play an important role in the pathogenesis of asthma." (PMID 23008731, 2012). "A defect in IL-10 production was first identified in patients with MS, followed by a report of defective IL-10 production in patients with asthma and altered cytokine production was shown in patients with rheumatoid arthritis." (PMID 23144765, 2012). "Higher levels of IL-10 were detected in the CVA group compared with those observed in the classic asthma group throughout the observation period." (PMID 22927709, 2012). "According to that, we chose the three cytokines, transforming growth factor β (TGF-β), IL-10, and IL-17A for further discussion, focusing on their effects on asthma as well as on lung tumor and their relevance as possible therapeutic targets." (PMID 22855687, 2012). "The results of the present study showed that the levels of IL-10 in patients of asthma increased significantly (P = 0.001) in comparison to controls." (PMID 23226977, 2012). "Calcitriol has previously been shown to correct defective IL-10 production in steroid resistant asthma patients, and in vitro studies have shown an effect on T cells isolated from patients with Crohn's disease." (PMID 23144765, 2012). "We observed an increase in the level of IL-1β, IL-4, IL-5, IL-6, IL-8, and IL-10 in asthma patients as compared to the controls." (PMID 23226977, 2012). "The number of Foxp3+ cells tended to increase and their activity, measured by IL-10 production, increased after sitostanol treatment in PBMCs from asthma patients compared to controls by 32.3% (p = 0.077) and 13.3% (p<0.05), respectively." (PMID 23091602, 2012). "The level of IL-10 in serum secreted by NKT cells in asthma group was decreased significantly than that of the control group (P < 0.01) especially in 48 hours, while that of SIT group was increased significantly (P < 0.01)." (PMID 23008731, 2012). "Taking the mentioned findings together, the conclusion arises that IL-10 plays an important role in asthma and airway tolerance." (PMID 22855687, 2012). "High levels of pro-inflammatory IL-6 and IL-17 cytokines and low levels of an anti-inflammatory cytokine IL-10 have been observed in asthmatic patients, suggesting that a functional vitamin D insufficiency/deficiency may be responsible for an increased probability of developing asthma." (PMID 21494627, 2011). "The association of adjusted IL-10 and IFN-γ with asthma, wheezing, and bronchial hyperresponsiveness was also investigated in this population." (PMID 23724228, 2011). "Addition of vitamin D3 and DEX to regulatory T (Treg) cells enhances IL-10 secretion, and administration of vitamin D3 to patients with GC-R asthma reportedly enhances the subsequent IL-10 induction in response to DEX." (PMID 23675190, 2010). "Frequencies of CD4+ T cells producing IL-10 as well as CD4+ T cells producing IL-13 was positively correlated with the duration of asthma (r = 0.44, P < .004 and r = 0.4, P < .01, resp)." (PMID 21197090, 2010). "Regulatory differences between parental and pediatric asthma were reflected by six of the eleven mediators analyzed (eotaxin, IL-4, IL-5, IL-10, IL-12, TNFα)." (PMID 21179211, 2010). "Interleukin(IL)-10 has a broad spectrum of anti-inflammatory effects and there is evidence that its secretion is reduced in asthma and COPD." (PMID 27713276, 2010). "A number of SNPs in the IL10, CYP24A1, CYP2R1, IL1RL1 and CD86 genes were modestly associated with asthma and atopy (p < 0.05)." (PMID 19852851, 2009). "In the replicate samples, SNPs in the IL10 and CYP24A1 genes were again modestly associated with asthma and atopy (p < 0.05)." (PMID 19852851, 2009). "Two-gene models implicating functional variants in the IL10 and VDR genes as well as in the IL10 and IL1RL1 genes were associated with asthma (p < 0.0002)." (PMID 19852851, 2009).